LEP (leptin)
Diseases named in the same sentence as LEP in open-access papers (continued):
Sharing a sentence is not in itself a finding about the gene and the disease.
Sepsis (continued). "However, whether leptin administration before sepsis induction mediates its protective effects during sepsis through blood pressure regulation is not known." (PMID 30618812, 2018). "Furthermore, leptin predicted sepsis-related in-hospital deaths." (PMID 28919840, 2017). "The adipokines leptin and adiponectin are involved in the inflammatory process, and they may modulate key processes during sepsis development such as cytokine production, immune cell proliferation and endothelial function through interaction with other cytokines and their receptors." (PMID 28919840, 2017). "After adjustment for BMI leptin remained associated with sepsis in men, but not in women." (PMID 28919840, 2017). "This might reflect a counteracting function of ghrelin and leptin in sepsis." (PMID 25844479, 2015). "We hypothesised that leptin would attenuate the HPA axis response to sepsis." (PMID 24578293, 2014). "We hypothesised that leptin attenuates the HPA axis response to sepsis." (PMID 24578293, 2014). "Serum leptin concentrations were measured during treatment in the ICU to investigate whether leptin is activated in critical illness, has diagnostic values for sepsis and/or multiple organ failure and whether leptin may serve as a prognostic predictor for survival in the ICU and long term." (PMID 24669245, 2014). "This idea is also supported by an ex vivo study by others demonstrating that continuous exposure of IL-1 or TNF-α provides a signal to downregulate leptin in human adipose tissue, though acute inflammation such as sepsis may rather upregulate circulating leptin levels transiently." (PMID 22685600, 2012). "Therefore, our results support the hypothesis that leptin might be involved in the pathogenesis of a systemic inflammatory response during sepsis possibly acting as an anti-inflammatory protein." (PMID 22973876, 2012). "Therefore, the present findings might reveal another effect of DAA during sepsis, i.e. the up-regulation of the hormone leptin under circumstances of ongoing systemic inflammation." (PMID 22973876, 2012). "However, the role of specifically leptin during severe sepsis is not yet completely understood." (PMID 22973876, 2012). "Appetite-inhibitory hormones such as the adipokine leptin and the gut hormone PYY initially rise in sepsis while ghrelin, an appetite-stimulatory peptide hormone released from the stomach, falls." (PMID 37144447, 2023). "We found an increase in the expression of IL-6, IL-8, IL-10, IL-18, IL-33, IP-10, MIF, MIP1a, MIP1β, MIP3a, LEPTIN, GCSF, MCSF, and ESelectin in sepsis plasma compared to w/o sepsis and HC." (PMID 35681439, 2022). "Leptin is thought to curb inflammatory responses and improve host survival, leading to improved ICU and sepsis management." (PMID 30254810, 2018). "Furthermore, we found that inertia in the leptin response to sepsis in the acute phase was related to worse outcome, which is an intriguing finding that could be of outermost importance for the understanding of the triggers of an adequate immune response to a life-threatening sepsis." (PMID 28919840, 2017). "In line with published data, we found significantly increased leptin, MCP-1, and resistin levels after onset of sepsis." (PMID 27601939, 2016). "Although these increased leptin levels may diminish the negative ghrelin associated effects in sepsis, as was observed in the hfd group, we suggest that ghrelin levels were increased before leptin levels resulting in a misbalance of function to the side of ghrelin." (PMID 25844479, 2015). "Therefore, we asked whether additional ghrelin treatment in sepsis might affect leptin levels." (PMID 25844479, 2015). "To detect any influences of ghrelin on leptin levels, we measured leptin levels before and after CLP-induced sepsis." (PMID 25844479, 2015). "The results revealed that leptin, combined with temperature, platelet and WBC counts and heart rate are an effective logistic regression model for the diagnosis of sepsis." (PMID 24669245, 2014).
Sepsis (continued). "We investigated the direct effects of leptin on the HPA axis response to acute lipopolysaccharide (LPS) administration in rats, a model of the neuroimmunological changes observed in sepsis in both rodents and humans." (PMID 24578293, 2014). "Serum leptin increases in SIRS and sepsis and is strongly related to circulating levels of TNF-α, IL-6." (PMID 20230641, 2010). "On the second day of ICU admission, significant elevation of leptin, IL-6 and TNF-α occurred in the SIRS and sepsis groups." (PMID 20230641, 2010). "In a recently published study, it has been reported that serum leptin concentrations are low in all critically ill patients on admission to the ICU, with lowest levels in sepsis patients." (PMID 20871818, 2010). "It had been reported that circulating leptin levels were low in critically ill patients upon admission to the ICU, possibly due to an acute stress response, with lowest levels in patients with sepsis." (PMID 20871818, 2010). "Multivariate analysis demonstrated that survival in septic patients was not related to absolute leptin levels or the decline of leptin during prolonged sepsis." (PMID 39838305, 2025). "In humans, higher leptin levels have been observed in survivors of sepsis compared to non-survivors, underscoring leptin’s protective role in immune responses during infection." (PMID 40095902, 2025). "Previous studies have also failed to observe an increase in leptin levels in inflammatory conditions such as sepsis, experimental endotoxemia, and HIV infection despite an elevation in IL-6 levels." (PMID 39200926, 2024). "Other studies reported that leptin increases in severe burns, but non-survivors and patients with sepsis presented lower leptin serum levels when compared with severely burned patients who had no sepsis and had survived." (PMID 39062875, 2024). "Sepsis patients showed an increase in a few of the pro-inflammatory cytokines i.e., IL-6, IL-8, IL-18, IL-33, IP-10, MIF, MIP1a, MIP1β, and MIP3a, along with the growth factors i.e., LEPTIN, GCSF, MCSF and ESelectin." (PMID 35681439, 2022). "Among appropriate for gestational age infants without sepsis, IL-6 and leptin were strongly correlated (R=0.6, P<0.001)." (PMID 35197933, 2022). "Tschöp and colleagues reported higher leptin levels in patients recovered from sepsis compared to that of nonsurvivors." (PMID 33907162, 2021). "The authors found out that a serum leptin threshold of 38 μg/L can differentiate sepsis from noninfectious SIRS, with a sensitivity of 91.2% and a specificity of 85%." (PMID 33907162, 2021). "Low leptin levels were found in prolonged sepsis, but findings revealed that this was not related to survival." (PMID 33907162, 2021). "Yousef and colleagues found out that a serum leptin cut-off level of 38 μg/L has a key role in differentiation between sepsis and noninfectious SIRS, with a sensitivity of 91.2% and specificity of 85%." (PMID 33907162, 2021). "Leptin production is regulated by inflammatory stimuli, including lipopolysaccharide, TNF-α, IL-6, and IL-1β, and plasma leptin levels increase during acute infection, inflammation, or sepsis." (PMID 32655492, 2020). "In humans, the patients’ recovered from sepsis had higher leptin levels compared to that of non-survivors." (PMID 32824322, 2020). "In line, a smaller series of patients with severe sepsis revealed no significant regulation of serum leptin levels in septic disease." (PMID 31569348, 2019). "Clinical studies in humans have reported higher leptin concentrations in survivors than in non-survivors of severe sepsis and septic shock." (PMID 30254810, 2018). "In humans, three-fold higher leptin levels were reported in the patients' recovered from sepsis compared to that of non-survivors." (PMID 29868503, 2018). "Genetic rescue of leptin signaling in the CNS of db/db mice improved the survival in sepsis compared to non-rescued db/db mice." (PMID 29868503, 2018).
Sepsis (continued). "Repeated analysis after omitting the NSMC- or MSP cohort did not alter the results and leptin remained predictive of an event of sepsis." (PMID 28919840, 2017). "Sepsis-induced leptin increases generated a stabile body temperature in sepsis while the ghrelin treatment itself did not alter body temperature." (PMID 25844479, 2015). "Septic patients displayed significantly higher leptin serum concentrations compared with those of the non-septic controls (mean leptin concentration, 11.67 mg/dl in the sepsis group versus 4.82 mg/dl in the control group; P<0.001)." (PMID 24669245, 2014). "Our findings suggest that leptin does not influence HPA function or IL1β secretion in a rat model of LPS-induced sepsis, and thus that leptin is unlikely to be involved in the acute-phase endocrine response to bacterial infection in rats." (PMID 24578293, 2014). "Serum leptin concentrations and additional markers of sepsis were compared between the sepsis group (n=128) and the non-sepsis group (n=203)." (PMID 24669245, 2014). "Both negative and positive correlations between leptin levels and clinical outcome in patients with sepsis have been reported." (PMID 25398383, 2014). "In the present study, it was observed that the serum leptin concentrations were significantly higher in the sepsis group than in the non-sepsis group." (PMID 24669245, 2014). "Accordingly, patients suffering from severe sepsis revealed increased leptin serum levels, while patients treated with DAA revealed increasing leptin serum levels after complete treatment with DAA (i.e. 96 hours infusion) at day 3 and 5 compared to untreated septic patients." (PMID 22973876, 2012). "Thus, high sOb-R concentrations neutralized leptin-mediated STAT3 signaling and anorexic responses in rats and protected mice against experimentally-induced sepsis." (PMID 22545089, 2012). "Minor changes of leptin serum levels in septic patients are reported with various slight increase or decrease during the course of sepsis, not being related either to survival or to metabolic and hormonal changes." (PMID 22272381, 2012). "A recent study found that serum LEP is a powerful biomarker that helps to differentiate sepsis from the non-infectious systemic inflammatory response syndrome in critically ill patients." (PMID 21943151, 2011). "A positive correlation was found among leptin, IL-6 and TNF-α in both SIRS and sepsis groups." (PMID 20230641, 2010). "Upon admission to Medical Intensive Care Unit (ICU), free leptin and soluble leptin-receptor serum concentrations were determined in 137 critically ill patients (95 with sepsis, 42 without sepsis) and 26 healthy controls." (PMID 20871818, 2010). "The concentration of leptin fails to differentiate the onset of sepsis from a non-complicated course." (PMID 20230641, 2010). "The present study was conducted to determine the role of serum leptin at early diagnosis and differentiation between patients with manifestations of SIRS and those with sepsis in patients suffering from a broad range of diseases in ICU and its correlation with other biomarkers." (PMID 20230641, 2010). "Critically ill patients with sepsis on ICU admission had even lower circulating admission levels of RBP4 and leptin than did patients without sepsis." (PMID 19589139, 2009). "Leptin is also produced by inflammatory regulatory cells and upregulated in response to several inflammatory mediators (i.e., LPS and inflammatory cytokines such as TNF-α, IL-6, and IL-1β), so that serum leptin concentrations highly increase during acute infection, inflammation, and sepsis." (PMID 33804765, 2021). "Interestingly, a decline of leptin serum levels was found during prolonged sepsis, which was, however, not related to survival." (PMID 31569348, 2019).
Sepsis (continued). "When sepsis occurs, multiple redundant inflammatory cytokines are released into the blood stream, including tumor necrosis factor-α (TNF-α), interleukin-6 (IL-6), leptin, C-reactive protein (CRP) and procalcitonin (PCT), which are important for mediating the inflammatory response." (PMID 24669245, 2014). "Thus, leptin affects the immune system by influencing CD4+ T-cell polarization, B-cell homeostasis as well as renal macrophage infiltration and modulates the severity of sepsis." (PMID 22545089, 2012). "However, the pathophysiological role of leptin during severe sepsis is currently not elucidated in detail." (PMID 22973876, 2012). "Although leptin and leptin-receptor serum concentrations do not differ in patients with critical illness or in the subgroups of patients with and without sepsis from healthy controls, serum leptin in critically ill patients is closely correlated with the patients' BMI and metabolic alterations." (PMID 20871818, 2010). "Patients with sepsis had lower levels of leptin and RBP4 than did nonseptic patients." (PMID 19589139, 2009). "However, if leptin administration improves hypotension during sepsis is not known." (PMID 30618812, 2018). "Thus, leptin may suppress the HPA axis, impairing its protective role in sepsis." (PMID 24578293, 2014). "However, the role of leptin during sepsis is not yet fully elucidated." (PMID 22973876, 2012). "In conclusion, our findings show that an acute dose of 2 mg/kg leptin fails to influence HPA function or IL1β secretion, 4 h after injection, in a rat model of acute 25 μg/kg LPS-induced sepsis." (PMID 24578293, 2014). "From day 1 to day 3 of sepsis, leptin levels increased in patients treated with DAA compared to patients without treatment of DAA (p < 0.10) (leptin concentrations, Day 1: DAA+, mean = 18991 pg/ml, ±SEM = 6009 pg/ml." (PMID 22973876, 2012). "The exact mechanisms contributing to increased leptin mRNA and protein expressions after administration of DAA in human adipocytes and patients suffering from severe sepsis were not determined in this study." (PMID 22973876, 2012). "CRP, leptin, IL-6 and TNF-α were compared among the following groups: sepsis group (n = 40), SIRS group (n = 34) and non-SIRS group (n = 32)." (PMID 20230641, 2010). "We observed low circulating levels of adiponectin, RBP4, and leptin in critically ill patients on admission to the ICU, with lowest values in patients with sepsis, but also in patients not critically ill under acute surgical stress." (PMID 19589139, 2009). "Patients suffering from severe sepsis without treatment of DAA revealed significantly higher serum concentrations of leptin compared to healthy controls (n = 45, mean = 12116 pg/ml, ± SEM = 1945 pg/ml) (leptin concentrations, Day 1: DAA-, mean = 30175 pg/ml, ±SEM = 4203 pg/ml." (PMID 22973876, 2012).
hypertriglyceridemia (83 papers, 2009 to 2025). A laboratory test result indicating elevated triglyceride concentration in the blood. "Severe hypertriglyceridemia in the HHTg rats was associated with low-grade chronic inflammation, characterized by significantly elevated serum levels of leptin, IL-6, and PAI-1." (PMID 39858414, 2024). "A growing body of evidence demonstrates that HFD promotes MeS associated with impaired glucose tolerance, hypertriglyceridemia, increased leptin levels, among others, being relevant for the progression of age-related cognitive decline and AD." (PMID 33535619, 2021). "Liver-specific deficiency of PPARγ, in the leptin mutant obese mouse (ob/ob), leads to a unique imbalance in triglycerides characterized by low levels of triglycerides in the liver and serum hypertriglyceridemia." (PMID 24130751, 2013). "In contrast, leptin was only positively associated with hypertriglyceridemia after adjustment for FMI (OR in the highest quartile = 2.90, 95%CI 1.46∼5.77, Ptrend = 0.006)." (PMID 21347230, 2011). "Low levels of leptin and very low levels of adipokines may be associated with metabolic complications, such as type 2 diabetes mellitus, hypertriglyceridemia, metabolic dysfunction-associated steatotic liver disease (MASCD), and severe insulin resistance." (PMID 40565151, 2025). "Leptin-deficient mice have the potential for hypertriglyceridemia and hypercholesterolemia." (PMID 26305254, 2015). "In these animals, leptin supplementation largely prevented the dysmetabolic phenotype associated to undernutrition during gestation, characterized by increased fat accumulation and other metabolic syndrome-related disturbances, such as insulin resistance, hypertriglyceridemia, and hepatic steatosis." (PMID 34523036, 2022). "Metabolic workup showed new-onset diabetes mellitus, a very low high-density lipoprotein, severe hypertriglyceridemia, and undetectable leptin/adiponectin levels." (PMID 39935494, 2025). "Metrelepin is a recombinant human leptin approved to treat congenital generalized lipodystrophies; it improves glycemic control and alleviates hypertriglyceridemia." (PMID 40565151, 2025). "Serum leptin levels were increased in the offspring of women with hypertriglyceridemia during pregnancy, and were positively correlated with mTG levels." (PMID 33431976, 2021). "Consistent with the animal study results, we observed elevated serum leptin levels and blood pressure in the offspring born to women with gestational hypertriglyceridemia." (PMID 33431976, 2021). "There are many confounding factors of HFD‐induced hypertriglyceridemia in animal models, including weight gain, body composition, and the levels of hormones such as leptin, insulin, and ghrelin." (PMID 33943005, 2021). "On the other hand, she was taking omega-3 fatty acids for hypertriglyceridemia and her plasma leptin levels were low." (PMID 33916827, 2021). "Leptin crosses the blood brain barrier informing the brain about the feeding and nutritional status of the rest of the body and hypertriglyceridemia which occurs during starvation inhibits leptin transport." (PMID 26693381, 2015). "It was reported that a diet containing 10% fructose leads to maternal hypertriglyceridemia and altered maternal and fetal leptin signaling." (PMID 25800472, 2015). "Reduced leptin and insulin sensitivities contribute to hypertriglyceridemia induced by fructose ingestion." (PMID 24672546, 2014).